IL6 (interleukin 6)
Diseases named in the same sentence as IL6 in open-access papers (continued):
Sharing a sentence is not in itself a finding about the gene and the disease.
cancer (continued). "Chronic elevation of IL-6 in the TME also maintains the inflammatory state and creates a niche that is favorable for the progression of cancer." (PMID 41376630, 2025). "Elevated levels of TNF-α, IL-6, IFN-γ, and IL-12p70 confirmed strong immune activation, highlighting its potential as a cancer treatment platform." (PMID 41228373, 2025). "The levels of cytokines, such as IL-6 and TNF-α, are elevated, stimulating cell cycle progression and preventing apoptosis, thereby allowing cancer cells to proliferate uncontrollably." (PMID 40255569, 2025). "Therefore, IL-6 may be important for the growth of malignant tumors." (PMID 41179937, 2025). "IL-6 activates downstream targets via phosphorylation of ERK1/2 (p-ERK1/2) and STAT3 (p-STAT3) in cancer cells." (PMID 39858048, 2025). "In cancer progression, STAT3 mainly promotes oncogenic transcription through well‐established phosphorylation‐dependent pathways, such as the JAK/STAT3 or IL‐6/STAT3 axes, which upregulate cyclin D1, Bcl‐xL and survivin." (PMID 40464702, 2025). "Inflammatory cytokines like IL‐6 and TNF‐α released by cancer cells activate adipocytes in the TME, shifting them from storage to lipolysis mode and releasing free fatty acids for cancer cells to utilize." (PMID 40391753, 2025). "By decreasing IL-6, STAT3, NF-κB, PGE-2, COX-2, and TNF-α levels, combining the effects of prebiotics and probiotics helps lower inflammation and inhibit cancer-promoting pathways, offering a promising strategy for CRC prevention and treatment." (PMID 41322104, 2025). "In particular, we examine the role of circRNAs in TGF‐β, IL‐6, IL‐10, TNF‐α, VEGF, FGF, PDGF, and chemokine signaling in cancer." (PMID 40356340, 2025). "TAMs secrete cytokines, such as IL-6 and TNF-α, that inhibit T-cell activation while promoting the proliferation of cancer stem cells." (PMID 40861435, 2025). "The qPCR analysis of the same samples demonstrated that mRNA expression levels of IL‐6, VEGF, IL‐8, and TNF‐α were significantly upregulated in cancer tissues compared to adjacent tissues, with Fold Changes ranging from 2.5 to 4.0 (p < 0.01)." (PMID 40596746, 2025). "Elevation of IL-6 and CRP are well-recognized features of cancer progression and considered predictors of poor prognosis and survival, and are found to be associated with chemotherapy resistance in breast, colorectal, lung, and gastrointestinal cancers." (PMID 40523478, 2025). "In CAR-T cell therapy, PE is used to remove inflammatory cytokines, such as IL-6, TNF-α and other molecular cytokines that are released after the interaction between cancer cells and CAR-T cells." (PMID 40630950, 2025). "Exercise has been shown to regulate inflammatory factors such as interleukin-6 (IL-6) and tumor necrosis factor-alpha (TNF-α), reducing cancer-related side effects and helping restore muscle mass homeostasis." (PMID 40104495, 2025). "For instance, the production of proinflammatory cytokines such as IL-6, IL-1β, and TNF-α is downregulated by the omega-3 PUFA eicosapentaenoic acid (EPA) in healthy people and cancer patients." (PMID 40430444, 2025). "SASP-induced IL-6 and IL-8 release has been shown to accelerate EMT in cancer cells, thereby enhancing their migratory and invasive capabilities." (PMID 41463272, 2025). "Their self-renewal ability is sustained by interactions with the TME, where factors like IL-6, TGF-β, and HIF-1 promote proliferation, angiogenesis, and survival, underscoring the complex interplay driving cancer dynamics." (PMID 40260236, 2025). "The Mφ-CM contained a number of EMT inducers, including CHI3L1, IL-10, IL-6, IL-8, and TNF-α, which are known to play a role in cancer metastasis, migration, invasion, chemotaxis, and endothelial cell junction retraction." (PMID 40678259, 2025). "Among the key molecular mediators of cancer cachexia are inflammatory proteins such as Growth Differentiation Factor-15 (GDF-15) and interleukin-6 (IL-6)." (PMID 40807373, 2025).
cancer (continued). "In HNCs, it has been observed that SASP-induced IL-6 and IL-8 secretion promotes epithelial-to-mesenchymal transition (EMT), thereby increasing cancer cell motility and invasiveness." (PMID 41463272, 2025). "In this context, NEK9 functions as an effector of the interleukin-6 (IL-6)/STAT3 signaling pathway, which contributes to cancer metastasis." (PMID 41154634, 2025). "IL-6/STAT3 activation enhances resistance to apoptosis and promotes cancer cell proliferation, invasion, and metastasis." (PMID 41458591, 2025). "C3 is dominated by infiltration of neutrophils and pro-inflammatory cytokines (such as IL-6, TNF-α) and is commonly found in tumors with HPV-related cancers or a background of chronic inflammation." (PMID 41474538, 2025). "A clinical cancer study found that, in the acupuncture group, CD3+ T and CD4+ T cell levels increased, while IL-6 and CRP levels decreased." (PMID 40098703, 2025). "IL‐6 and IL‐23 contribute to Th17 differentiation, maintain inflammatory environments in the TME, and support cancer growth 151]." (PMID 40547943, 2025). "Among the tested compounds, ECH147 exhibited the most consistent and pronounced inhibitory effect on IL-6 expression at both the mRNA and protein levels, particularly in SW1116 cancer cells and CCD-841CoN normal cells." (PMID 41256010, 2025). "Inflammatory mediators like Interleukin-6 (IL-6) and Tumor Necrosis Factor-alpha (TNF-alpha) activate STAT3 and NF-κB signaling pathways to promote cancer cell proliferation." (PMID 40475789, 2025). "In the present study, we found that TNF, IFN, IRF1 and IRF5, IL-6, IL-1β, and CCL3 were upregulated in EBV-positive SCC25 cancer cells compared to EBV-negative SCC25 cancer cells." (PMID 39941858, 2025). "Both IL‐6 and GDF‐15 are involved in cancer‐related cachexia, with their elevated levels predicting more severe muscle wasting, reduced physical function and diminished ability to withstand the stresses of surgery and cancer treatment." (PMID 41380167, 2025). "Our study identified core genes (ALB, BCL2, EGFR, IL-6, and STAT3) enriched in cancer pathways, suggesting a potential link between cancer-related metabolic dysregulation and fatigue." (PMID 40435272, 2025). "One of the main mechanisms is the excessive production and secretion of cancer-related cytokines, particularly tumor necrosis factor alpha (TNF-α), interleukin-6 (IL-6), interleukin-1 (IL-1), and C-reactive protein (CRP)." (PMID 40862802, 2025). "IL‐6 is known to activate autophagy and contribute to chemoresistance in CRC, while the 14‐3‐3 pathway is integral to cancer stress adaptation." (PMID 41472855, 2025). "The release of MCP1 by IL-6 signaling in human vascular endothelial cells induces the activation of the JAK/STAT3 and PI3K/AKT pathways, also in various cancer cells." (PMID 40430040, 2025). "The JAK-STAT3 pathway, predominantly activated by cytokines such as IL-6, IFNγ, LIF, and OSM, plays a central role in cancer cachexia pathogenesis." (PMID 40704145, 2025). "Recent studies have highlighted the important role of pro-inflammatory cytokines released after surgical resection, especially TGFβ-1, IL-6, and HGF, in promoting epithelial–mesenchymal transition (EMT) and enhancing cancer cell metastasis potential." (PMID 40227834, 2025). "In OC-TME, elevated IL6 levels upregulate the expression of PDL1 and CTLA4 in cancer cells, which inhibits T cell activity and serves to escape the immune response." (PMID 40427188, 2025). "This review summarizes changes in three major pro-inflammatory cytokines—IL-6, TNF-α, and IL - 1β—in MDD and their influence on cancer progression." (PMID 41000397, 2025). "IL-6 and IL-8 secretion was suppressed in PRKCSH-knockout (KO) cancer cells, disrupting cytokine-mediated immune suppression." (PMID 41350724, 2025). "IFN-γ induces systemic inflammatory responses by increasing the levels of IL-6 and TNF-α, which lead to changes in energy metabolism and neural function, resulting in fatigue symptoms in cancer patients." (PMID 39980555, 2025).
cancer (continued). "Various cytokines, including interleukin 6 (IL-6), were present at high levels in adipocyte-OTSCC co-cultures, and inhibition of IL-6 signalling markedly reduced cancer cell migration." (PMID 41271789, 2025). "Inflammation also raises circulating levels of inflammatory cytokines that promote cancer, such as C-reactive protein (CRP) and interleukin-6 (IL-6)." (PMID 40007994, 2025). "IL-6 and TNF-alpha are pro-inflammatory cytokines that have been shown to significantly impact various cancer-related biological processes, including cell proliferation, angiogenesis, invasion, and metastasis." (PMID 40558287, 2025). "IL-6 activates the JAK/STAT signaling pathway, which enhances cancer cell proliferation and resistance to apoptosis." (PMID 40255569, 2025). "Administration of recombinant IL-6 to healthy volunteers or cancer patients has been shown to stimulate VP, ACTH, and cortisol secretion suggesting that peripheral IL-6 affects the HPA axis and VP secretion in human." (PMID 41210498, 2025). "For instance, n-3 PUFAs have been shown to suppress levels of IL-6 and TNF-α in cancer patients, as well as reduce IL-17A-mediated inflammation and IL-11 expression in hepatocytes during acetaminophen-induced hepatotoxicity." (PMID 40704145, 2025). "Evidence indicates that inflammatory markers, including C reactive protein (CRP), interleukin-6 (IL-6), systemic inflammatory response index (SII), and neutrophil-to-lymphocyte ratio (NLR), are critical factors influencing cancer prognosis." (PMID 40313883, 2025). "Previous studies have shown that autophagy promotes the secretion of protumorigenic factors—including IL-6, IL-8 and MMP2—in Ras-driven cancers and facilitates IL-1β secretion through unconventional secretory pathways." (PMID 41408407, 2025). "The current view is that, on the one hand, activated immune cells secrete large amounts of inflammatory and other mediators in cancer (e.g., NF-κB, TNF-α, IL-1β, IL-6, etc.), affecting the function of distant organs, such as the heart." (PMID 40182041, 2025). "The abnormally changed cytokines such as TNF-α and IL-6 in MAE can destroy tissue matrix, promote cancer cell metastasis, and induce the production of VEGF, a key factor crucial for MAE progression." (PMID 41044610, 2025). "Using a 23-plex bead-based immunoassay, we found that knockdown of LDHC significantly increased the levels of cancer cell-derived GM-CSF, IFN-γ, MCP-1, and CXCL1, while reducing IL-6 and Gal-9 levels." (PMID 40108668, 2025). "Since IL-6 and CCL2 are representative markers of inflammatory fibroblasts, our results indicate that cancer cell-derived DKK1 induces lung fibroblasts to adopt an inflammatory phenotype." (PMID 40025612, 2025). "These M1-like TAMs secrete IL6, supporting EMT and cancer stem cells via the JAK/STAT3 pathway, thus creating a positive feedback loop." (PMID 39941858, 2025). "A recent study revealed that XIST activates the IL-6/STAT3 pathway to promote inflammation and cancer stem cell self-renewal." (PMID 40407589, 2025). "We included the protein biomarkers, HE4, CA19-9, CEA, and AFP, which are all commonly used in clinical cancer detection, as well as prolactin (PRL) and interleukin-6 (IL-6), which have been reported in previous studies." (PMID 40502685, 2025). "This activation subsequently triggers the IRE1α–XBP1 axis, promoting the expression of PD‐L1 and the secretion of cancer cell‐promoting factors such as IL‐10, VEGF, IL‐6, and IL‐8." (PMID 40547943, 2025). "Future analyses in the main REPRIEVE trial population will relate IL-6 and other inflammatory markers to MACE, cancer endpoints, and other comorbidities to better guide the development of novel therapies for different long-term comorbidities in PWH." (PMID 40924496, 2025). "Pro-inflammatory cytokines like IL-1, IL-6, and TNF-α are often elevated in cancer, contributing to cancer cachexia and reduced treatment efficacy." (PMID 41387645, 2025).
cancer (continued). "Inflammatory factors (IL-6, STAT3, YAP1, NF-κB, COX-2/PGE2, and NO) induce stemness, which promotes cancer progression." (PMID 40244228, 2025). "Their interaction with epithelial and cancer cells triggers inflammatory cytokines (e.g., interleukins IL-6, IL-17, IL-8) and pathways (e.g., NF-kB, STAT3), promoting epithelial-to-mesenchymal transition, immune chemoattractants, and cancer cell proliferation." (PMID 40230461, 2025). "Previous studies showed that CSNP has an inhibitory impact on the IL6 gene expression and an inducing effect on the PTEN gene expression in breast, and lung cancers." (PMID 40457310, 2025). "A meta-analysis examining serum inflammatory biomarkers following vitamin D supplementation in cancer patients revealed significant reductions in TNF-α, IL-6, and C-reactive protein (CRP) levels, while IL-10 levels remained unchanged." (PMID 39582404, 2025). "For instance, IL-6 has been observed to amplify toll-like receptor (TLR)-mediated cytokine production, suggesting its role in exacerbating inflammatory responses in cancer pain contexts." (PMID 40579593, 2025). "Mφ can activate the NF‐κB signaling pathway by secreting factors such as S100A9 and IL-6, which promotes the stemness of HCC cells and the self-renewal of cancer stem cells (CSCs), thus providing a pro‐tumorigenic niche for early HCC." (PMID 40621461, 2025). "In particular, the significant reduction in concentrations of IL-6, MCP-1, PDGF-BB by Polish propolis and quercetin seems to be important in cancer therapy." (PMID 40733274, 2025). "Pro-inflammatory cytokines like IL-6 and tumor necrosis factor-alpha (TNF-α) activate survival signaling pathways in cancer cells, such as the STAT3 and NF-κB pathways." (PMID 40356750, 2025). "Further, the enduring oxidative stress caused by changes in mitochondrial complex I activity reinforces critical pathways promoting cancer progression, including aspects of both profibrotic TGF-β signaling and proinflammatory IL-6 cytokine production." (PMID 39908263, 2025). "Previous studies have indicated that IL-6 and TNF-α were pro-inflammatory cytokines, which mediate in many inflammatory diseases and contribute to developing autoimmune disorders and cancer." (PMID 40109962, 2025). "In head and neck tumour cells (CAL27), exposure to IL-6 cytokines upregulated SNAI1 protein levels and enhanced cancer cell migration." (PMID 40371393, 2025). "IL-6-induced activities can be inhibited by ascorbic acid through the enhancement of TET2 activity, thereby presenting a novel concept for cancer treatment." (PMID 39872372, 2025). "TGF-β, TNF-α, IL-6, and IL-10 are a few pro-inflammatory cytokines that regulate TME in TNBC and promote cancer progression and invasiveness." (PMID 40933989, 2025). "Furthermore, phase I and II clinical trials demonstrated the efficacy of monoclonal antibodies against IL-6 and its receptor, either as single agents or in combination with other chemotherapeutic agents, radiation, and targeted therapies in various types of cancer." (PMID 40940764, 2025). "Targeting IL-6 can disrupt MDSC recruitment and support the anti-cancer ability of the immune system." (PMID 40109854, 2025). "In the VPP cancers, significant increases were observed in CXCL1, CXCL2, GZMB, IL6, CCL13, and CCL19, among others." (PMID 40361362, 2025). "Cytoskeletal regulators (MYL9, TAGLN) and transcription factors (SNAI2) promote EMT and cancer stemness, while PMEPA1, IL6, IL8, IGFBP3, INHBA, and VEGFA contribute to proliferation, angiogenesis, and immune modulation." (PMID 41009714, 2025). "First, it induces the production of proinflammatory cytokines such as TNF-α, IL-6, and IL-1β, as well as chemokines such as CXCL1 and CCL2, which recruit immune cells, stimulate angiogenesis, and enhance cancer cell proliferation." (PMID 40562870, 2025). "The concentrations of presepsin, PCT, IL-6 and CRP were prospectively measured in 57 FN episodes in 23 cases of malignant haematological diseases in children." (PMID 40961458, 2025).
cancer (continued). "In a subgroup analysis of the CNS and cancer, qigong and yoga showed increased BDNF and IL-6, respectively." (PMID 40281902, 2025). "For instance, the production of inflammatory cytokines IL-6 and TNF-α, which play a crucial role in cancer-related inflammation, depends also on TERT binding to NF-κB." (PMID 39858033, 2025). "Analysis of cytokine concentrations revealed significantly elevated levels of pro‐inflammatory cytokines, including TNF‐α, IL‐6, IL‐1β, IL‐8, and VEGF, in cancer tissues compared to adjacent tissues (Fold Change: 2.5–4.0, p < 0.05)." (PMID 40596746, 2025). "It tampers with key signals, including IL-6/STAT3, NF-κB, and ERK1/2, to limit immunosuppressive macrophages and disable cancer-cell survival pathways." (PMID 40490812, 2025). "Overexpression of inflammatory cytokines, such as IL-6, TGF-β, and TNF-α can trigger or inhibit cancer development." (PMID 41614883, 2025). "Paired qPCR results comparing cancer and adjacent tissues indicated elevated mRNA expression of IL6, JAK and STAT3 in cancer tissues, along with an increase in the activity of the IL6‐JAK‐STAT3 pathway, compared to adjacent tissues." (PMID 39893643, 2025). "In preclinical studies, IL-6 inhibition combined with immune checkpoint blockade (ICB) enhanced antitumor immunity and slowed tumor progression across various cancer models." (PMID 39796190, 2025). "There are over 600 myokines in human myocyte-conditioned medium, including myostatin, IL-6, IL-15, irisin, myonectin, decorin, SPARC and FSTL-1, some of which are involved in cancer suppression." (PMID 41300368, 2025). "One such drug, siltuximab, a chimeric anti-IL-6 antagonistic antibody, received FDA approval for treating multicentric Castleman disease and is currently being investigated for treating cancers." (PMID 39780187, 2025). "Evidence suggests that atorvastatin significantly reduces IL-6 and CRP levels in cancer patients, and other research has confirmed statin-mediated CRP reduction across various diseases and cell types." (PMID 40943351, 2025). "Previous studies have demonstrated the role of IL-6 signaling in promoting CD44 expression and its importance in conferring cancer stem cell properties." (PMID 40430044, 2025). "For example, NQO1 also inhibits cytotoxic cytokines including IL-6, IL-1B, and TNFα through TLR suppression in macrophages and microglia, a finding with clinical significance in both cancers and neurodegenerative disorders." (PMID 40946102, 2025). "Notably, CST1 isoform is involved in the regulation of key cellular pathways, such as Wnt, GSK3, AKT, and IL-6, linking it to inflammatory processes/immunological response, cell cycle regulation/cell senescence, antimicrobial activity, cancer progression, and metastatic spread." (PMID 40869198, 2025). "This aligns with recent literature emphasizing the role of IL-6 in activating STAT3 signaling, which in turn drives oncogenic pathways, including proliferation, survival, and stemness of cancer cells." (PMID 40612845, 2025). "The elevated levels of IL6 in the TME stimulate the production of pro-inflammatory cytokines and chemokines, further promoting cancer cell survival, proliferation, and migration to distant organs." (PMID 40427188, 2025). "The TLR-4-mediated pathway controls IL-6 and IL-8 production and induces anti-apoptotic protein XIAP in cancer cells, leading to PTX resistance." (PMID 40404908, 2025). "This regulation suppresses IL-6/IL-6R/STAT3 signaling activity, leading to reduced proliferation, migration, and invasiveness of cancer cells." (PMID 41179679, 2025). "Prominosomes-primed M2-like tumor-associated macrophages showed increased secretion of cytokines and chemokines, notably interleukin-6, compared to untreated cells leading to the activation of the STAT3 pathway in EV-donor cancer cells." (PMID 39881297, 2025).